TPCN2 (two pore segment channel 2)
Description:
Intracellular channel initially characterized as a non-selective Ca(2+)-permeable channel activated by NAADP (nicotinic acid adenine dinucleotide phosphate), it is also a highly-selective Na(+) channel activated directly by PI(3,5)P2 (phosphatidylinositol 3,5-bisphosphate). Localizes to the lysosomal and late endosome membranes where it regulates organellar membrane excitability, membrane trafficking, and pH homeostasis. Is associated with a plethora of physiological processes, including mTOR-dependent nutrient sensing, skin pigmentation and autophagy. Ion selectivity is not fixed but rather agonist-dependent and under defined ionic conditions, can be readily activated by both NAADP and PI(3,5)P2. As calcium channel, it increases the pH in the lysosomal lumen, as sodium channel, it promotes lysosomal exocytosis. Plays a crucial role in endolysosomal trafficking in the endolysosomal degradation pathway and is potentially involved in the homeostatic control of many macromolecules and cell metabolites (By similarity). Also expressed in melanosomes of pigmented cells where mediates a Ca(2+) channel and/or PI(3,5)P2-activated melanosomal Na(+) channel to acidify pH and inhibit tyrosinase activity required for melanogenesis and pigmentation. Unlike the voltage-dependent TPCN1, TPCN2 is voltage independent and can be activated solely by PI(3,5)P2 binding. In contrast, PI(4,5)P2, PI(3,4)P2, PI(3)P and PI(5)P have no obvious effect on channel activation. (Microbial infection) During Ebola virus (EBOV) infection, controls the movement of endosomes containing virus particles and is required by EBOV to escape from the endosomal network into the cell cytoplasm. (Microbial infection) Required for cell entry of coronaviruses SARS-CoV and SARS-CoV-2, as well as human coronavirus EMC (HCoV-EMC), by endocytosis.
Synonyms: TPC2; SHEP10
Tractability: Small molecule: a structure with a bound ligand is known; it belongs to a druggable protein family. Antibody: UniProt predicts a signal peptide or a membrane-spanning region. PROTAC: ubiquitination databases record sites on it; its protein half-life has been measured.
Gene: Protein-coding gene on chromosome 11 (69,048,850 to 69,136,316, forward strand). Ensembl gene ENSG00000162341.
Subcellular location: Late endosome membrane; Lysosome membrane; Melanosome membrane
Subcellular location (Human Protein Atlas): Nucleoli
Pathways (Reactome):
Transport of small molecules: Stimuli-sensing channels
Gene Ontology:
Molecular function: calcium channel activity; identical protein binding; intracellularly phosphatidylinositol-3,5-bisphosphate-gated monatomic cation channel activity; ligand-gated sodium channel activity; NAADP-sensitive calcium-release channel activity; phosphatidylinositol-3,5-bisphosphate binding; protein binding; protein kinase binding; voltage-gated calcium channel activity; voltage-gated sodium channel activity; monoatomic ion channel activity; voltage-gated channel activity
Biological process: calcium-mediated signaling; endocytosis involved in viral entry into host cell; intracellular calcium ion homeostasis; intracellular pH reduction; lysosome organization; negative regulation of developmental pigmentation; receptor-mediated endocytosis of virus by host cell; regulation of autophagy; sodium ion transmembrane transport; endosome to lysosome transport of low-density lipoprotein particle; monoatomic ion transmembrane transport; regulation of exocytosis; smooth muscle contraction; monoatomic ion transport; release of sequestered calcium ion into cytosol; response to vitamin D; transmembrane transport
Cellular component: endolysosome membrane; endosome membrane; late endosome membrane; lysosomal membrane; lysosome; melanosome membrane; cytosol; membrane
Genetic constraint (gnomAD): Loss-of-function variants: 91 observed, 110.86 expected, observed/expected ratio (o/e) 0.82, 90% interval 0.69 to 0.98. The upper end of that interval is the gene's LOEUF score, 0.98, which puts it in group 4 of 6, group 1 being the genes least tolerant of losing a copy. Missense variants: 995 observed, 988.99 expected, observed/expected ratio (o/e) 1.01, 90% interval 0.95 to 1.06. Synonymous variants: 405 observed, 412.32 expected, observed/expected ratio (o/e) 0.98, 90% interval 0.9 to 1.07.
Homologues: Orthologues: chimpanzee TPCN2 (99% identical), macaque TPCN2 (94% identical), dog TPCN2 (83% identical), guinea pig TPCN2 (82% identical), pig TPCN2 (81% identical), mouse Tpcn2 (73% identical), rat Tpcn2 (67% identical), tropical clawed frog nadsyn1 (61% identical), zebrafish tpcn2 (54% identical). Paralogues in human: CACNA1A (24% identical), SCN3A (24% identical), SCN2A (24% identical), CACNA1C (24% identical), SCN4A (24% identical), SCN1A (24% identical), SCN8A (24% identical), SCN9A (24% identical), CACNA1B (23% identical), SCN5A (23% identical), CACNA1E (23% identical), CACNA1D (23% identical), and 14 more.